CRP (C-reactive protein)
Diseases named in the same sentence as CRP in open-access papers (continued):
Sharing a sentence is not in itself a finding about the gene and the disease.
Sepsis (continued). "The percentage of patients with sepsis was higher in the groups that met the CRP criterion, while the percentage of patients categorized under neurology was higher in the groups that did not meet the CRP criterion." (PMID 40005032, 2025). "The results were promising in predicting sepsis, and the salivary CRP cut-off scores were comparable to with serum CRP levels." (PMID 39851610, 2025). "Repeat sepsis markers on day three showed declining trends (procalcitonin: 45 ng/mL; CRP: 120 mg/L), correlating with clinical improvement." (PMID 41552058, 2025). "The LR-based model integrating RDW, APACHE II score, and biomarkers (PCT, IL-6, CRP, cystatin C) effectively predicts the risk of AKI in children with sepsis, offering a valuable tool for early intervention and improved patient outcomes." (PMID 41281283, 2025). "We evaluated the prognostic predictive capabilities of heparin-binding protein (HBP) and C-reactive protein (CRP) at different time points in elderly patients with sepsis." (PMID 40568199, 2025). "Integrating AG trajectories with other biomarker trajectories, such as lactate and CRP, can enhance the predictive power for the prognosis of sepsis patients." (PMID 40822945, 2025). "In sepsis, CRP increases and positively correlates with the degree of infection, while ALB is often decreased." (PMID 40351994, 2025). "Both CRP levels (OR 1.01, p = 0.003) and leukocyte count (OR 1.16, p = 0.004) were significant predictors of sepsis." (PMID 40142700, 2025). "The prompt and robust elevation of CRP in systemic bacterial infections makes it a valuable early indicator of inflammation and sepsis." (PMID 41010302, 2025). "The present findings demonstrate a prohibitively high diagnostic error rate (approximately 44 % false positives) when CRP is used as a biomarker for sepsis diagnosis in adults." (PMID 41429071, 2025). "This study aimed to investigate calprotectin’s diagnostic performance in distinguishing sepsis from non-sepsis at ICU admission, to compare the performance of calprotectin with CRP, and to assess both biomarkers in subgroups of critically ill ICU patients." (PMID 40319081, 2025). "C-reactive protein and procalcitonin are known markers of inflammation and sepsis, and their elevation reflects the severity of the inflammatory response." (PMID 40299374, 2025). "Comparative studies between PSP and traditional sepsis biomarkers such as C-reactive protein (CRP) and procalcitonin (PCT) have also been published." (PMID 40863214, 2025). "Haemoglobin and white cell counts were within normal limits, excluding acute haemorrhage or sepsis, while a markedly elevated C-reactive protein (CRP) (106 mg/L) indicated localised inflammation consistent with cyst rupture." (PMID 41450364, 2025). "Elevated CRP is often correlated with an intense systemic inflammatory response, which often indicates a complication of the bacterial infection, such as sepsis or septic shock." (PMID 40230497, 2025). "Our multivariate analysis showed that elevated CRP and leukocyte levels were significant predictors of sepsis." (PMID 40142700, 2025). "Inflammatory conditions such as sepsis, autoimmune diseases, and certain malignancies can provide false-positive CRP test results that are unrelated to cardiovascular diseases." (PMID 41480420, 2025). "The current biomarkers used for sepsis diagnosis, e.g., c-reactive protein (CRP), interleukin-6 (IL-6), and procalcitonin (PCT), have achieved partial success because most of these biomarkers are associated with inflammation and are not specific to infection." (PMID 40002629, 2025). "Improved sepsis patients showed significantly different values between both initial and follow-up evaluations regarding nCD64%, hs-CRP, PLT, nCD64 MFI, ANC, Hb, and nCD11b MFI, and this was evident by the high Z values and the low p values for each of them." (PMID 40224545, 2025).
Sepsis (continued). "The proposed model using the Bayesian network approach with the combination of CRP, leukocyte count, and postoperative sTREM-1 showed promise for the diagnosis of sepsis." (PMID 40806505, 2025). "With regard to biomarkers, CRP was significantly elevated in myocarditis and sepsis, while D-dimer was particularly useful for identifying non-cardiac causes such as pulmonary embolism and aortic dissection." (PMID 41341294, 2025). "Positive CRP measurements are the current, extensively used tests to facilitate confirming the suspicion of sepsis, despite the concerning low sensitivity as seen not only in this study and others." (PMID 39937751, 2025). "This study evaluated the diagnostic performance of calprotectin and C-reactive protein (CRP) to distinguish between sepsis and non-sepsis on intensive care unit (ICU) admission." (PMID 40319081, 2025). "Tovalidate its functionality, the electrode was employed in an electrochemicalsensing experiment targeting the CRP biomarker as a critical biomarkerof sepsis." (PMID 41244407, 2025). "Serum levels of IL-40, a newly identified biomarker, and TNF-α, a classical proinflammatory cytokine, were highest in the LPS group, corroborating the successful establishment of the sepsis model and paralleling CRP elevation (p < 0.001)." (PMID 41196905, 2025). "The meta-analysis results revealed that RETN testing had a greater sensitivity than specificity, whereas CRP testing had a greater specificity than sensitivity for diagnosing sepsis in neonates and children." (PMID 40416430, 2025). "We concluded that nCD64 expression was superior to PCT and CRP in early detection of sepsis in patients with hematological malignancies during episodes of FN." (PMID 40369641, 2025). "Although CRP’s accuracy for early sepsis diagnosis is debated, it has shown promise as a prognostic indicator, with studies reporting higher mortality in children whose CRP levels failed to decline after initial treatment." (PMID 39858517, 2025). "The results showed that APACHE II, WBC, PCT, CRP, TNF-α, IL-6, and SOFA scores were the independent risk factors for the 28-day survival of patients with sepsis after high-dose CRRT (all p < 0.05)." (PMID 41393152, 2025). "Presepsin has emerged as a promising biomarker for the early diagnosis and prognosis of sepsis, offering distinct advantages over traditional inflammatory markers such as procalcitonin and CRP." (PMID 40804836, 2025). "Among inflammatory markers, CRP was 100 ± 70 mg/L, suggesting ongoing systemic inflammation or sepsis in most patients." (PMID 40149101, 2025). "In canine patients, elevated serum concentrations of CRP are observed quickly in various conditions, including babesiosis, leishmaniosis, leptospirosis, parvoviral enteritis, and sepsis." (PMID 41227463, 2025). "Given the immunologic overlap between PCAS and sepsis, we measured CRP and procalcitonin, along with hematologic indices." (PMID 41585252, 2025). "A recent large-scale multicenter randomized clinical trial compared procalcitonin (PCT)- and C-reactive protein (CRP)-guided monitoring protocols in critically ill patients with suspected sepsis." (PMID 40870363, 2025). "The dynamic fluctuations of C-reactive protein (CRP) and cell-free DNA (cfDNA) as biomarkers offer crucial insights into the pathophysiology of inter alia sepsis, myocardial infarction, and physical exertion." (PMID 40282303, 2025). "Early biomarkers of sepsis include C-reactive protein (CRP) and procalcitonin (PCT), which help distinguish bacterial infections from sterile inflammation." (PMID 40297590, 2025). "Due to suspected sepsis and rising C-reactive protein (CRP, 4,8 mg/dl), antibiotic treatment with meropenem was started at admission and stopped after 48 h after admission due to negative blood cultures." (PMID 40114164, 2025). "Our analysis revealed significantly higher CRP concentrations in patients with septic shock than in those diagnosed with sepsis (P < 0.05)." (PMID 40895306, 2025).
Sepsis (continued). "In the all-case analysis, the optimal cut-off level for CRP was higher in the following groups: 15.65 mg/dL for sepsis; 10.29 mg/dL for digestive; and 5.52 mg/dL for pulmonary." (PMID 40005032, 2025). "Consistent with findings from other studies, our data revealed that at hospital admission, patients with HLH were characterized by abnormal hepatic and blood cell tests, while those with severe sepsis exhibited elevated levels of CRP and PCT." (PMID 41321462, 2025). "NeoSep-SAA and comparator CRP test performance data from neonatal sepsis study (CCG vs. CNC, n = 714) in terms of sensitivity, specificity, PPV and NPV." (PMID 39937751, 2025). "C-reactive protein (CRP): CRP is one of the most used biomarkers for neonatal sepsis, measured in neonatal blood samples." (PMID 40003700, 2025). "A second, smaller increase in both CD34+ cells and CRP was observed during a sepsis episode in the second postnatal week." (PMID 41147034, 2025). "Biomarkers in the inflammatory cascade including C-reactive protein (CRP), Il-6 and TNF-α have been associated with AF; and these inflammatory biomarkers are significantly raised in sepsis." (PMID 39879166, 2025). "Using RCS, we analyzed the association between serum AREG levels, serum C-reactive protein (CRP) concentration, disease severity, and sepsis-related mortality." (PMID 40292295, 2025). "Significantly higher age, respiratory rate, heart rate, body temperature, leukocyte count, CRP, procalcitonin, neutrophil/lymphocyte ratio and plasma lactate levels in the sepsis group are indicators of systemic inflammation and tissue hypoperfusion." (PMID 41315982, 2025). "○Maintained cell viability, morphology and anti‐apoptotic effects.○Attenuation of sepsis‐induced MI○Decreased bacterial loads, CRP, and WBC levels.○Decreased myocardial inflammatory cytokine expression." (PMID 40599085, 2025). "In the available literature, PCT and CRP as prognostic factors for in-hospital mortality have been most frequently analyzed for populations composed solely of patients diagnosed with sepsis, adding a preference for their serial assessment." (PMID 40004075, 2025). "Here, we identified circulating predictors of distinct types of sepsis and hospital outcomes, highighting differences between commonly used laboratory variables, such as leukocyte and platelet counts, CRP, procalcitonin, lactate, and ferritin levels." (PMID 39950122, 2025). "Currently, various clinical laboratory markers are frequently employed to evaluate the severity of sepsis and track its progression, including biomarkers like C-reactive protein (CRP) and procalcitonin (PCT)." (PMID 40478888, 2025). "Infants with positive maternal Triple-I had a higher rate of NICU admissions and positive CRP but a lower rate of sepsis workup." (PMID 41039480, 2025). "Significantly higher serum IMA, homocysteine and MDA levels were observed in the severe sepsis with positive correlation with high-sensitivity C-reactive protein." (PMID 40413366, 2025). "The random forest has identified the following 10 descriptors as the most relevant: APACHE II, Creatinine, SOFA PaO2/FiO2, C-Reactive protein, bilirubin, BMI, age, morning glycemia, glycemia at admission and sepsis upon admission." (PMID 41026286, 2025). "CLU levels tend to decrease in patients with severe sepsis and qSOFA ≥2 and correlated inversely with pro‐inflammatory cytokines (IL‐6, TNFα) and inflammatory markers (CRP)." (PMID 40722110, 2025). "Dynamic indices offer valuable insights into the progression of sepsis, and trajectories of markers such as 24-h urine output, C-reactive protein, SBP, and SI have been used to predict patient outcomes." (PMID 40417677, 2025). "Procalcitonin and CRP have emerged as valuable biomarkers in distinguishing febrile neutropenia from sepsis, given their high specificity and sensitivity in detecting bacterial infections." (PMID 40688982, 2025).
Sepsis (continued). "Regarding the indications for PTGBD realization, the most common were worsening inflammatory markers despite appropriate antibiotic therapy (n = 50, 47.62%) and severe inflammatory status (C-reactive protein level > 300 mg/dL or sepsis) (n = 37, 35.24%)." (PMID 41302992, 2025). "C-reactive protein (CRP) is a widely used traditional inflammatory marker in sepsis; however, its predictive capability is relatively limited." (PMID 40568199, 2025). "Despite its moderate specificity for early identification of sepsis, we still used CRP as an important variable in our model for prediction of severe infection." (PMID 41291834, 2025). "Correlated with sepsis diagnosis, procalcitonin and C-reactive protein levels were increased at 4.9 ng/mL (2.9–13.9) and 15.6 mg/dl (8.2–23.0), respectively." (PMID 40647659, 2025). "The CRP-to-albumin ratio combines nutritional and inflammatory status and has been extensively examined as an independent prognostic marker in sepsis, infections, malignancies, and other diseases." (PMID 41010574, 2025). "Our study compares CRP and cfDNA as biomarkers of exercise stress, myocardial infarction, and sepsis." (PMID 40282303, 2025). "While CRP and PCT are widely used to assist in identifying sepsis, numerous studies have reported that their diagnostic and prognostic value is limited." (PMID 40478888, 2025). "Inflammatory mediators, such as cytokines and C-reactive protein, induce TF expression during sepsis." (PMID 40649892, 2025). "The percentage of patients with sepsis was higher in the groups that met the CRP criterion: 22.7% in the CRP+BMI+ group." (PMID 40005032, 2025). "In our study, the CRP + PCT combination emerged as the best predictor for sepsis, demonstrating 85% sensitivity, 80% specificity, and an AUC of 0.85." (PMID 41011807, 2025). "Laboratory investigations revealed markedly elevated sepsis markers: procalcitonin of 99 ng/mL (normal: <0.5 ng/mL) and CRP of 241 mg/L (normal: 0-5 mg/L)." (PMID 41552058, 2025). "C-reactive protein (CRP) is a potential candidate useful in ruling out sepsis and can be a potential substitute for blood cultures." (PMID 40322340, 2025). "A comparative evaluation with other established prognostic biomarkers in sepsis, such as C-reactive protein (CRP), neutrophil count, and the neutrophil-to-lymphocyte ratio (NLR), is also warranted." (PMID 41357484, 2025). "In this retrospective observational study of calprotectin and CRP as diagnostic markers of sepsis at ICU admission, the main finding was that calprotectin was inferior to CRP in diagnosing sepsis at ICU admission." (PMID 40319081, 2025). "CRP, on the other hand, had a lower sensitivity of 61% but a higher specificity of 90.5%, indicating that it is more effective at ruling out non-sepsis cases." (PMID 40242671, 2025). "In sepsis patients, high CRP levels delay the repair of damaged vascular and organ tissues, prolonging the duration of organ dysfunction." (PMID 41393152, 2025). "Signs of incipient sepsis, including leucocytosis (18.7 x109/L) and an increase in C-reactive protein (CRP) (303 mg/L) despite intravenous antibiotic therapy, led to a re-admission." (PMID 40034399, 2025). "C-reactive protein (CRP), a general marker of inflammation, remains widely utilized for sepsis prognostication and monitoring treatment response." (PMID 40724799, 2025). "Serum markers such as procalcitonin (PCT), interleukin-6 (IL-6), C-reactive protein (CRP), and cystatin C have been widely studied in the context of sepsis and kidney injury." (PMID 41281283, 2025). "There are cases in which the CRP level is already high at the time of hospitalization, as in the case of sepsis a few days after onset, or when it reaches its peak within a few days, such as following surgery." (PMID 40005032, 2025). "As presented, patients with sepsis frequently had elevated inflammatory markers C-reactive protein, procalcitonin, and fibrinogen, and leukocytosis with neutrophilia." (PMID 40076848, 2025).
Sepsis (continued). "The treatment significantly reduced serum levels of key biomarkers of sepsis, including C-reactive protein (CRP), lactate (Lac), tumor necrosis factor-alpha (TNF-α) and interleukin-6 (IL-6), and dose-dependently improved the survival of septic mice." (PMID 41157235, 2025). "In terms of blood parameters, platelet count and hemoglobin levels were significantly lower, whereas the CRP levels were significantly higher in the septic shock group than in the sepsis group (P < 0.05)." (PMID 40895306, 2025). "Current criteria for sepsis diagnosis, which are based on markers such as CRP and leukocyte counts, have significant limitations." (PMID 40806505, 2025). "CRP is a classical acute-phase reactant synthesized by hepatocytes in response to cytokines such as IL-6 and increases in conditions like infection and sepsis." (PMID 40941711, 2025). "In the Vit E and LPS + Vit E groups, vitamin E administration led to a significant reduction in CRP levels compared to the Sepsis group (p < 0.05), indicating a clear anti-inflammatory effect." (PMID 41196905, 2025). "In conclusion, this study presented a logistic regression-based model combining RDW, APACHE II, and additional biomarkers (PCT, IL-6, CRP, and cystatin C) to predict AKI risk in children with sepsis." (PMID 41281283, 2025). "Recent research confirms the significance of biomarkers such NLR, IL-6, CRP, procalcitonin, and lactate levels in diagnosing and monitoring sepsis, systemic infection, and SIRS." (PMID 40870412, 2025). "Logistic regression identified CRP and PCT as the strongest univariate predictors of sepsis, but after adjustment for age, sex, BMI, and comorbidities, CRP lost significance, whereas VD and sCD14-ST remained independent predictors." (PMID 41153764, 2025). "Uncontrolled systemic inflammation: Persistently elevated CRP in sepsis patients was a direct sign of an unresolved systemic inflammatory response." (PMID 41393152, 2025). "They concluded that APACHE II is better than the CRP/Albumin ratio in predicting post-operative complications and mortality in sepsis patients." (PMID 40091950, 2025). "C-reactive protein (CRP) is a well-known, atypical immunochemical marker associated with various pathological conditions, such as bacterial infections, sepsis, autoimmune disorders, malignancies, and myocardial infarction." (PMID 40558585, 2025). "In some infants, such as subjects 4 and 8, elevated levels of inflammatory markers (CRP and IL-6) and sepsis coincided with increased circulating CD34+ cell counts." (PMID 41147034, 2025). "PCT and CRP are the most widely used biomarkers for sepsis, with some suggesting that PCT offers greater specificity and prognostic value, although this remains debated." (PMID 40650251, 2025). "The subsequent rise in CRP and procalcitonin likely reflected a dual process—superimposed sepsis and progressive inflammatory cardiomyopathy." (PMID 41375765, 2025). "Symptoms can range from severe sepsis to vague indicators like elevated CRP or leukocyte counts, particularly with Staphylococcus epidermidis." (PMID 39802368, 2025). "CRP, produced by hepatocytes during the systemic inflammatory response, is commonly used as a biomarker to monitor the progression of sepsis." (PMID 41464553, 2025). "The aim of our study was to compare the procalcitonin-to-albumin ratio (PAR) and C-reactive protein(CRP)-to-albumin ratio (CAR) in predicting sepsis and its severity in children and to know which one is better." (PMID 40351994, 2025). "With the Bayesian model, we found that a 100% probability of sepsis was related to postoperative blood concentrations of CRP above 71 mg/dL, a leukogram above 14,000 cells/μL, and sTREM-1 concentrations above the cutoff point (283.53 pg/mL)." (PMID 40806505, 2025). "Although CRP and other acute-phase proteins effectively distinguished patients with sepsis from healthy individuals, they had limited ability to differentiate sepsis subgroups by outcomes." (PMID 40864331, 2025).